COQ3 (coenzyme Q3, methyltransferase)
Description:
O-methyltransferase required for two non-consecutive steps during ubiquinone biosynthesis (By similarity). Catalyzes the 2 O-methylation of 3,4-dihydroxy-5- (all-trans-decaprenyl)benzoic acid into 4-hydroxy-3-methoxy-5-(all-trans-decaprenyl)benzoic acid (By similarity). Also catalyzes the last step of ubiquinone biosynthesis by mediating methylation of 3-demethylubiquinone into ubiquinone (By similarity). Also able to mediate the methylation of 3-demethylubiquinol-10 into ubiquinol-10 (By similarity).
Synonyms: UG0215E05; bA9819.1; DHHBMT; DHHBMTASE
Tractability: Antibody: UniProt places it where antibodies can reach, with medium confidence. PROTAC: ubiquitination databases record sites on it; its protein half-life has been measured.
Gene: Protein-coding gene on chromosome 6 (99,369,401 to 99,394,207, reverse strand). Ensembl gene ENSG00000132423.
Subcellular location: Mitochondrion inner membrane
Subcellular location (Human Protein Atlas): Nucleoplasm; Mitochondria
Pathways (Reactome):
Metabolism: Ubiquinol biosynthesis
Gene Ontology:
Molecular function: 3-demethylubiquinol 3-O-methyltransferase activity; 3-demethylubiquinone 3-O-methyltransferase activity; O-methyltransferase activity; polyprenyldihydroxybenzoate methyltransferase activity; protein binding
Biological process: glycerol metabolic process; ubiquinone biosynthetic process
Cellular component: mitochondrial inner membrane; mitochondrion; ubiquinone biosynthesis complex; extrinsic component of mitochondrial inner membrane; mitochondrial matrix
Genetic constraint (gnomAD): Loss-of-function variants: 17 observed, 24.41 expected, observed/expected ratio (o/e) 0.7, 90% interval 0.48 to 1.04. The upper end of that interval is the gene's LOEUF score, 1.04, which puts it in group 4 of 6, group 1 being the genes least tolerant of losing a copy. Missense variants: 335 observed, 354.69 expected, observed/expected ratio (o/e) 0.94, 90% interval 0.86 to 1.03. Synonymous variants: 139 observed, 133.31 expected, observed/expected ratio (o/e) 1.04, 90% interval 0.91 to 1.2.
Homologues: Orthologues: chimpanzee COQ3 (98% identical), macaque COQ3 (93% identical), pig COQ3 (81% identical), dog COQ3 (79% identical), rabbit COQ3 (79% identical), guinea pig COQ3 (76% identical), mouse Coq3 (72% identical), rat Coq3 (69% identical), tropical clawed frog coq3 (45% identical), zebrafish coq3 (44% identical), Drosophila melanogaster Coq3 (30% identical), Caenorhabditis elegans coq-3 (28% identical).
Diseases named in the same sentence as COQ3 in open-access papers:
COQ3 is named in the same sentence as 9 diseases in open-access papers, as found by Europe PMC text mining. Sharing a sentence is not in itself a finding about the gene and the disease. The quoted sentences say what the papers report.
esophageal cancer (2 papers, 2021 to 2022). A primary or metastatic malignant neoplasm involving the esophagus. "COQ3 has been shown to have an important role in the prognosis of esophageal cancer." (PMID 36189217, 2022). "COQ3 is the most significant survival-altering gene in EAC, which also could be potentially susceptible to the complex I inhibitor metformin, which has already been shown to be beneficial in esophageal cancer with combination therapy." (PMID 34307352, 2021).
astrocytomas (1 paper, 2022). "Taken together, we have demonstrated that lower CoQ10 levels and protein levels of COQ3, COQ5, COQ6, COQ7, COQ8A, and COQ9 were associated with higher tumor grades and lower CS activity or COX II level in human astrocytomas." (PMID 35204836, 2022). "The levels of COQ3, COQ5, COQ6, COQ7, COQ8A, and COQ9, but not of COQ4, were lower in Grade IV astrocytoma tissues than in controls or low-grade (Grades I and II) astrocytomas, but PDSS2 levels were higher in astrocytoma tissues than in controls." (PMID 35204836, 2022).
esophageal squamous cell carcinoma (1 paper, 2022). Esophageal squamous cell carcinoma (ESCC) is a type of esophageal carcinoma (EC) that can affect any part of the esophagus, but is usually located in the upper or middle third. "However, COQ3 gene expression was found to be upregulated in esophageal squamous cell carcinoma and was associated with poor prognosis, hinting at a potentially unique role of COQ3 in humans." (PMID 36552517, 2022).
Obesity (1 paper, 2022). Accumulation of substantial excess body fat. "Thus, obesity leads, at least in part, to the onset of AD by compromising mitochondrial function, while PPARGC1α and COQ3 play key roles in this process." (PMID 36568118, 2022).
COQ3 also shares sentences with these, for which no sentence is quoted: Anxiety (1 paper); breast carcinoma (1); depression (1); ischemia (1); tumor (1).